TRAF3IP3 (TRAF3 interacting protein 3)
Diseases named in the same sentence as TRAF3IP3 in open-access papers (continued):
Sharing a sentence is not in itself a finding about the gene and the disease.
TRAF3IP3 also shares sentences with these, for which no sentence is quoted: cerebral infarct (2 papers); acute myeloid leukemia (1); atherosclerosis (1); breast tumors (1); diabetes (1); glioblastoma (1); Graves disease (1); hepatocellular carcinoma (1); pancreatic adenocarcinoma (1); primary immunodeficiency (1); Salmonella Infections (1); small cell lung carcinoma (1); testicular germ cell tumor (1); thymoma (1).